APC (APC regulator of Wnt signaling pathway)
Diseases named in the same sentence as APC in open-access papers (continued):
Sharing a sentence is not in itself a finding about the gene and the disease.
colitis (25 papers, 2010 to 2025). Inflammation of the colon. "While mutations that aberrantly activate the Wnt pathway (e.g., APC) are found in over 85% of sporadic CRCs, in colitis-associated CRC mutations in the Wnt pathway are far less frequent." (PMID 35260534, 2022). "Muc2 deficient mice, known to develop spontaneous colitis, have been shown to robustly increase colon tumorigenesis when combined with APC mutation." (PMID 24997475, 2014). "Furthermore, APC mutations demonstrate late in colitis-associated CRC." (PMID 39858011, 2025). "For example, loss of APC function is a common and early event in sporadic CRC, while it is a much less frequent, and usually late, event in the colitis-associated dysplasia-carcinoma sequence." (PMID 21059221, 2010). "Furthermore, APC was less frequently mutated in CACs originated from pancolitis (4 of 47; 9%) than in CAC with limited colitis (6 of 11; 55%; p < 0.01 by Fisher’s exact test)." (PMID 29416670, 2018). "Also, experimental colitis was shown to increase tumorigenesis in APC+/Min mice through an iNOS-dependent mechanism." (PMID 27050089, 2016). "Furthermore, detailed analysis of the kinetics of acquisition of the mutational profile indicates that APC mutations are one of the earliest events in sporadic CRC pathophysiology, whereas in colitis-associated CRC, APC mutations occur later at the stage of high-grade dysplasia." (PMID 35260534, 2022). "Furthermore, the WT formulation used in our study contained turmerones, which have demonstrated their effectiveness in preventing CRC in mouse models, but these models used CRC, which developed from a background of colitis rather than an inherited mutation in the tumor suppressor gene APC." (PMID 36553450, 2022). "This may suggest that Fusobacterium induce oncogenesis downstream of the APC pathway and the tumorigenesis does not depend on pre-existing colitis condition because the colitis mice did not develop colon tumors after F. nucleatum introduction." (PMID 30374420, 2018). "Intriguingly, no colitis or enteritis was observed in any of the collected mice, suggesting that pharmacological inhibition of USP7 could be a safe option for patients with germline APC mutation." (PMID 36669491, 2023). "Therefore, APC is unlikely to have a gatekeeper function in colitis, and alternative mechanisms drive the Wnt activation signaling that drives cell proliferation or, alternatively, continuous inflammation and reparation provide a proliferative drive sufficient to substitute for APC lesions." (PMID 29652830, 2018).
hepatoblastoma (25 papers, 2011 to 2025). Hepatoblastoma (HB) is a malignant hepatic tumor and is the most common pediatric liver cancer. "Germline mutations in the APC gene increases hepatoblastoma risk via dysregulated WNT/β-catenin signaling in patients with familial adenomatous polyposis, and 11p15.5-imprinting defects or paternal uniparental disomy causes BWS." (PMID 40684183, 2025). "CTNNB1 (encoding β-catenin), APC and Axin mutations can be detected in up to 80% of cases of hepatoblastoma, indicating that the Wnt/β-catenin signaling pathway plays a vital role in the formation of hepatoblastoma." (PMID 35200654, 2022). "Previous studies have already suggested testing for APC mutations in children with extracolonic manifestations as hepatoblastoma, osteoma and Gardner fibroma." (PMID 29368261, 2018). "Many reports have found the presence of APC germline mutations associated with hepatoblastoma especially in the kindreds of FAP." (PMID 29190888, 2017). "Even in patients with apparently sporadic hepatoblastomas, germline APC mutations are identified in about 10%." (PMID 29190888, 2017). "The development of hepatoblastoma in this BWS infant can be explained by predisposition of UPD at 11p15.5 as well as possibly of APC and PALB2 mutations and later by somatic events with CTNNB1 somatic mutation and 1q gain acting as driver alterations." (PMID 29190888, 2017). "Examples of this include the incidental finding of a cancer predisposition syndrome due to an APC gene deletion when investigating a patient with features of 22q11.2 syndrome (DiGeorge syndrome) leading to early surveillance for hepatoblastoma that was successfully detected and treated." (PMID 39945861, 2025). "Additionally, germline APC mutations were reported in two studies in 10% and 14% of 29 patients with apparently sporadic hepatoblastoma." (PMID 35158896, 2022). "Mutation of the APC was detected in hepatoblastoma patients with a family history of FAP." (PMID 34367972, 2021). "In addition, four samples harbored germline truncating mutations in APC, another well-known hepatoblastoma driver gene, of which three were accompanied with additional somatic APC alterations." (PMID 32656360, 2020). "In addition, there has been a report of APC missense mutations in cases of hepatoblastoma; however, these cases all featured childhood disease onset, and we were unable to determine whether the patients developed adenomatous polyposis." (PMID 29535845, 2018). "Its molecular pathogenesis has similarities to that of hepatoblastoma, with abnormalities in the adenomatous polyposis coli (APC)/beta-catenin pathway and chromosome 11p." (PMID 36507125, 2022). "Hepatoblastoma is associated with FAP, which is an autosomal-dominant cancer predisposition syndrome caused by germline mutations in APC." (PMID 30619485, 2018). "To further extend the knowledge on BWS-associated hepatoblastoma development, we performed WES of a hepatoblastoma in a BWS infant with paternal UPD on chromosome 11p15.5 and germline APC mutation in this study." (PMID 29190888, 2017). "Early studies identified genetic mutations in CTNNB1, APC, AXIN1, AXIN2 in hepatoblastoma." (PMID 40684183, 2025). "In addition, adenomatous polyposis coli (APC) was also found within this sub-cluster that is known as driver gene for colorectal, pancreatic, desmoid, hepatoblastoma, and glioma cancers." (PMID 35439935, 2022). "Although the importance of beta-catenin-stabilizing mutations was reconfirmed by the high mutation rate of CTNNB1/APC, the presence of the other genetic lesions was not sufficient to explain the clinical heterogeneity of hepatoblastoma." (PMID 32656360, 2020). "Moreover, the inactivation of the APC gene, located on chromosome 5, has been observed in 67%‐89% of sporadic hepatoblastoma cases, while chromosome 11 aberrations may play an important role in hepatoblastoma pathogenesis in patients with BWS." (PMID 33236528, 2021).
hepatoblastoma (continued). "As a result, aberrant DNA methylation at the APC, CDH1, MT1G, RASSF1A and SOCS1 promoters were reported in hepatoblastoma." (PMID 36212481, 2022). "Although the APC and PALB2 germline mutations were not predicted as being pathogenic, further studies are necessary to conclude whether these two mutations play a synergistic role for the tumorigenesis of hepatoblastoma." (PMID 29190888, 2017).
hereditary nonpolyposis colorectal cancer (25 papers, 2003 to 2025). "In hereditary non-polyposis colon cancer (HNPCC), APC is wild type but β-catenin is mutated in its N-terminal phosphorylation sites." (PMID 17020613, 2006). "CTNNB1 mutations are found in 5% of human CRC with and without corresponding mutations in APC especially in hereditary nonpolyposis colorectal cancer (HNPCC) patients where the frequency of CTNNB1 mutation rises." (PMID 25162504, 2014).
medulloblastoma (25 papers, 2009 to 2025). A malignant, invasive embryonal neoplasm arising from the cerebellum. "An APC mutation was detected in a patient with a primary diagnosis of medulloblastoma who developed a malignant mesenchymal tumor as a tertiary malignancy in our study cohort." (PMID 39860595, 2025). "Regarding the origin of brain tumors in TS, glioblastomas are associated with MMR gene mutations, specifically in the MLH1 gene, whereas medulloblastomas are associated with APC gene mutations (about 40% of patients with TS develop a medulloblastoma)." (PMID 36768460, 2023). "It is estimated that germline APC mutations are associated with a 92 times higher risk for developing medulloblastomas than in the general population." (PMID 37746264, 2023). "We also reported a rare case of siblings with WNT-activated medulloblastomas associated with APC germline mutation in a South American patient." (PMID 37746264, 2023). "Genomic analysis showing XRCC3 alterations suggested radiotherapy as contributing factor to the progression of LFS-associated medulloblastoma, and demonstrated different mechanisms of APC inactivation in the FAP-associated tumors." (PMID 35978432, 2022). "Mutations in the APC gene in medulloblastoma have been known for some time and very recently, germline mutations were identified in a large series of patients with medulloblastoma using NGS analysis." (PMID 30523493, 2019). "APC gene is one of the consensus medulloblastoma predisposition genes and patients develop specifically WNT-activated type of tumors." (PMID 30523493, 2019). "Other less common mutations are found in sporadic medulloblastomas, including APC, AXIN1, and AXIN2, which are also keys to this pathway." (PMID 25101241, 2014). "It was observed in Turcot syndrome that in the case of patients with a mutation in the APC gene, in 79%, a medulloblastoma appeared, whereas in patients with the intestinal traits indicating mutations in the DNA repair genes – a glioma developed." (PMID 24148210, 2013). "It was originally linked to medulloblastoma through studies of Turcot syndrome, in which germline mutations in the APC gene have been identified." (PMID 19293793, 2009). "We identified P/LP variants in four of the six medulloblastoma genes: APC, ELP1, GPR161, and SUFU." (PMID 39184053, 2024). "This variant is located in a region of the APC gene associated with a higher risk of developing extracolonic tumors, which may explain the development of the two reported medulloblastomas." (PMID 37746264, 2023). "Therefore, the fact that ALK expression is positive in APC mutated tumor reinforces the usefulness of this marker for detection of the WNT type of medulloblastoma." (PMID 30523493, 2019). "Moreover, germline mutations of the Wnt pathway inhibitor APC predispose to Turcot syndrome in which medulloblastomas may occur." (PMID 25101241, 2014). "For patients with WNT-activated medulloblastomas CTNNB1 wild type, referral for genetic risk cancer assessment and germline APC sequencing is recommended." (PMID 37746264, 2023). "The prognosis for medulloblastoma patients with APC germline alteration is quite favorable with standard-of-care treatment." (PMID 38139220, 2023).
medulloblastoma (continued). "Landmark genomic studies have shown that 97% of WNT-driven medulloblastomas can be explained by somatic mutations in the CTNNB1 gene (~90%) and germline mutations in APC (~10%), which are mutually exclusive." (PMID 37746264, 2023). "CTNNB1 mutations are present in 90% of WNT-activated medulloblastomas; mutations in β-catenin, APC and AXIN1 have also frequently been identified in medulloblastoma." (PMID 35328644, 2022). "The mutational status of APC and CTNNB1 (β-catenin) was investigated in 33 CNS PNETs and 22 medulloblastomas." (PMID 19293793, 2009). "CNS tumors, most commonly medulloblastoma, though relatively rare, are also reported in patients with familial adenomatous polyposis (FAP), caused by germline mutations of the tumor suppressor gene adenomatous polyposis coli (APC)." (PMID 40469416, 2025). "In addition, we analyzed the changes of proteins (APC, CTNNB1, DDX3X, PTEN, BCOR) associated with medulloblastomas in CB at the four developmental stages." (PMID 37400444, 2023). "Considering that CTNNB1 wild-type cases may exhibit APC germline mutations, our study suggests a higher incidence (~30%) of hereditary WNT-activated medulloblastomas in the Latin-Iberian population." (PMID 37746264, 2023). "Therefore, tumor with the presence of APC mutation and monosomy of chromosome 6 can be classified as the WNT type of medulloblastoma." (PMID 30523493, 2019). "There was no case with PTCH, APC, or β-catenin mutations, known to be present in subsets of medulloblastomas." (PMID 29908563, 2018). "This is exemplified by the fact that in cases of sporadic brain gliomas or medulloblastomas no mutations in the APC gene have been reported." (PMID 24148210, 2013). "A previous study demonstrated that disruption of APC/C function using CARP-1 functional mimetics significantly downregulated MMP expression, specifically MMP-10, in medulloblastoma cells, supporting our rationale." (PMID 40136519, 2025). "No mutations were found in the mutation cluster region of APC in 20 CNS PNET and 19 medulloblastoma primary tumours sequenced." (PMID 19293793, 2009).
intestinal cancer (24 papers, 2012 to 2025). "The genes with the highest posterior probability of being associated with bowel cancer alone were APC (0.48) and GAPDH (0.48)." (PMID 40073867, 2025). "It is known that germline mismatch repair (MMR) gene mutations, together with APC gene mutations, contribute significantly to inherited bowel cancer." (PMID 35154239, 2021). "Mice deficient in an enhancer element Myc-335 that lies 335kb upstream of Myc are protected from APC (Adenomatous polyposis Coli) mutation-induced intestinal cancer." (PMID 32183428, 2020). "Adenomatous polyposis coli (APC) is mutated in more than 80% of patients with intestinal cancers including an autosomal dominant inherited condition familial adenomatous polyposis (FAP)." (PMID 30096840, 2018). "Mutation in the adenomatous polyposis coli (APC) gene results in the formation of spontaneous intestinal cancers." (PMID 30111276, 2018). "APC deficiency in models of intestinal cancer strongly suppresses tumorigenesis due to a defect in microtubule stabilization." (PMID 26049416, 2015). "Several other mice models of intestinal cancers have also been created, by introducing constitutive truncating mutations of APC in the germ-line." (PMID 22509309, 2012). "Our results provide scientific evidence that supports Riccardin D as a potential chemopreventive regimen for intestinal cancers derived from APC gene mutation." (PMID 22432006, 2012). "Importantly, these mice are more protected from APC mutation-induced intestinal cancer compared to mice deficient in only Myc-335." (PMID 32183428, 2020). "In the article titled “Crypt stem cells as the cells-of-origin of intestinal cancer,” which was the fifth co-cited paper, Clevers, H investigated the role of APC in the development of intestinal cancer using an LGR5 knock-in mouse model." (PMID 41194856, 2025). "As the sequence identity of the human and mouse APC proteins exceed 89%, the mouse represents a suitable model to study the involvement of APC truncations in intestinal cancer." (PMID 37927787, 2023). "Another study reported that monensin (10 mg/kg) reduced tumor volume in the APC+/Min intestinal cancer mouse model." (PMID 37370314, 2023). "In this case-control study, mutations in 8 genes (APC, ATM, MLH1, FANCD2, MSH3, MSH6, PMS1, and RAD51D) were found to be associated with bowel cancer and were present in 3.5% of patients with bowel cancer." (PMID 35154239, 2021). "Super-TDU treatment of adenomatous polyposis coli (APC) mutant mice (APCmin/+) (a mouse model typically used for colorectal and intestinal cancer) also significantly reduces the number and size of spontaneous adenomas without exhibiting detectable toxicity." (PMID 33467099, 2021). "Cross-talk between the WNT and MAPK signaling pathways has been documented due to APC loss and KRAS mutation in intestinal cancer." (PMID 34830178, 2021). "Mutations in APC, ATM, and MLH1 were associated with the highest risks of bowel cancer." (PMID 35154239, 2021). "Thus, intestinal tumourigenesis requires constitutive activation of the canonical Wnt pathway, although the aetiology of APC and β-catenin mediated intestinal cancer is different." (PMID 27196929, 2016). "For example, in the absence of the tumour suppressor APC, Kaiso‐deficient mice were resistant to intestinal cancer, suggesting that Kaiso might be an oncogene." (PMID 35851744, 2022).
intestinal cancer (continued). "The coexistence of APC alterations with PIK3CA mutation may be partially explained by a previous study using a mouse model with PIK3CA mutation, which demonstrated that the PIK3CA mutation alone was insufficient to initiate intestinal tumorigenesis in intestinal cancers." (PMID 30115035, 2018). "In intestinal cancer, a daily small dose of high-fructose corn syrup enhanced tumor growth in adenomatous polyposis coli (APC)-mutant mice, independent of obesity or metabolic syndrome." (PMID 37559908, 2023).